MEF2C (myocyte enhancer factor 2C)
Diseases named in the same sentence as MEF2C in open-access papers (continued):
Sharing a sentence is not in itself a finding about the gene and the disease.
pulmonary fibrosis (1 paper, 2022). Chronic progressive interstitial lung disorder characterized by the replacement of the lung tissue by connective tissue, leading to progressive dyspnea, respiratory failure, or right heart failure. "In conclusion, our study shows that MOBT alleviated pulmonary fibrosis through the lncITPF–hnRNP-l-complex-targeted MEF2c signaling pathway." (PMID 36014574, 2022). "Then, the MEF2c expression was analyzed by Western blot in the MRC-5 cells treated with TGF-β1 for different times to confirm the change in MEF2c in the pulmonary fibrosis cell model." (PMID 36014574, 2022). "This study proved that MOBT alleviated pulmonary fibrosis through downregulating the lncITPF–hnRNP-l-complex-targeted MEF2c signaling pathway in vitro and in vivo." (PMID 36014574, 2022). "Briefly, MOBT alleviated pulmonary fibrosis through the lncITPF–hnRNP-l-complex-targeted MEF2c signaling pathway." (PMID 36014574, 2022). "This work found that MOBT blocked MEF2c alternative splicing to prevent pulmonary fibrosis by reducing the formation of the lncITPF–hnRNP L complex, and that the lncITPF–hnRNP L could be a therapeutic drug target in pulmonary fibrosis." (PMID 36014574, 2022).
pulpitis (1 paper, 2020). Inflammation of the dental pulp. "Collectively, it can be concluded that MEF2C promotes transcription and interaction between PECAM1 and CXCR4, therefore promoting inflammatory responses in pulpitis samples." (PMID 33425898, 2020). "A transcription factor myocyte-enhancer factor 2 (MEF2C) was predicted and validated as a positive regulator of either PECAM1 or CXCR4, which activated the NF-κB signaling pathway and promoted pulpitis progression." (PMID 33425898, 2020). "Subsequently, we further examined the expression of and correlation between MEF2C and PECAM1 and CXCR4 in the dental tissues of rats in the Sham and Pulpitis groups." (PMID 33425898, 2020).
retinitis pigmentosa (1 paper, 2022). Retinitis pigmentosa (RP) is an inherited retinal dystrophy leading to progressive loss of the photoreceptors and retinal pigment epithelium and resulting in blindness usually after several decades. "Notably, at the MIR9-2 locus, MEF2C interacts with the gene CETN3 which is associated with retinitis pigmentosa and located over 1 Mb away." (PMID 36207300, 2022).
sensorineural hearing loss (1 paper, 2025). "Furthermore, immune infiltration analysis reveals significant correlations between FRGs (e.g., MEF2C with NK cells, PANX2 with M1 macrophages) and pro-inflammatory subsets, suggesting that ferroptosis may amplify cochlear inflammation—a known driver of sensorineural hearing loss." (PMID 40353062, 2025).
Sepsis (1 paper, 2025). Sepsis is defined as life-threatening organ dysfunction caused by a dysregulated host response to infection. "Recent research has revealed a reduction in MEF2C expression in rats with CLP-induced sepsis, and increasing MEF2C levels can mitigate ALI, reduce lung inflammation, and reduce apoptosis." (PMID 39901167, 2025). "Overall, miR-223-3p in LPS-EVs contributes to sepsis-induced ALI by priming AMs for autophagy and ferroptosis through the MEF2C/Hippo signaling pathway." (PMID 39901167, 2025).
soft tissue sarcoma (1 paper, 2014). A malignant neoplasm arising from muscle tissue, adipose tissue, blood vessels, fibrous tissue, or other supportive tissues excluding the bones. "Compared with normal tissues and non-RMS pediatric soft-tissue sarcomas, only MEF2C showed significant and consistent up-regulation in RMS samples (also shown are MYOD and MET, genes that associate with RMS), data that point toward MEF2C as influential in RMS." (PMID 25491943, 2014).
Splenomegaly (1 paper, 2015). Abnormal increased size of the spleen. "Patients with high MEF2C expression were younger (P < 0.001) and more likely presented with hepatomegaly (P = 0.006) or splenomegaly (P < 0.001)." (PMID 26487643, 2015).
stable angina (1 paper, 2018). "In a previous clinical study, increased expression of specific cardiac markers (Nkx2-5, gata-4, and mef2c) in PBMNCs, and increased number of CD34+/CXCR4+ and CD34+/CD117+ stem cells in PB were observed in ST-elevated MI patients compared to patients with stable angina and healthy Controls." (PMID 30485279, 2018).
Stroke (1 paper, 2024). Sudden impairment of blood flow to a part of the brain due to occlusion or rupture of an artery to the brain. "Neuronal specific Mef2c depletion reduced cerebral level of CflarR and cFLIPR (translated by CflarR), while mitigated neuron necroptosis and neurological deficits following stroke in hyperlipidemic mice." (PMID 39648651, 2024). "To further verify that neuronal CflarR splicing isoform upregulated by Mef2c could aggravate post‐stroke necroptosis in the context of HFD, we employed immunostaining and western blot to measure the expression level of necroptotic markers." (PMID 39648651, 2024). "To further evaluate the impact of neuronal specific Mef2c depletion on the ischemic brain injury and post‐stroke neurological functions, we subjected HFD‐treated Mef2cfl/fl or Emx1CreMef2cfl/fl mice to MCAO, and examined the brain injury with MAP2 and IgG double staining and behavioral tests." (PMID 39648651, 2024). "Moreover, the neurological outcome assessed by the mGarcia score, as well as the adhesive removal and grid walking tests were improved in HFD Emx1CreMef2cfl/fl mice up to 28 days following MCAO, suggesting ablation of neuronal Mef2c ameliorates post‐stroke neurological deficits especially." (PMID 39648651, 2024). "Neuron‐specific ablation of Mef2c reduced CflarR and cFLIPR expression, thus alleviating neuronal necroptosis and neurological deficits in HFD‐treated mice after stroke." (PMID 39648651, 2024).
T-cell leukemia (1 paper, 2016). A malignant disease of the T-lymphocytes in the bone marrow, thymus, and/or blood. "To investigate whether mutations in the reported repressive STAT5 TFBS located in the promoter region of MEF2C were implicated in T-cell leukemia, we performed sequence analyses of a 750 bp stretch in seven selected T-ALL cell lines (CCRF-CEM, JURKAT, MOLT-16, LOUCY, PEER, PER-117, RPMI-8402)." (PMID 27322685, 2016).
Tetralogy of Fallot (1 paper, 2022). A congenital cardiac malformation comprising pulmonary stenosis, overriding aorta, ventricular septum defect, and right ventricular hypertrophy. "Conditional deletion of Mef2c in the anterior second heart field results in embryos with DORV, tetralogy of Fallot, and transposition of the great arteries." (PMID 35736367, 2022).
thymoma (1 paper, 2015). A neoplasm arising from the epithelial cells of the thymus.
tongue squamous cell carcinoma (1 paper, 2021). A squamous cell carcinoma that arises from the tongue. "This is consistent with a recent study demonstrating that patients of tongue squamous cell carcinoma with high relative MEF2C (myocyte enhancer factor 2C) expression had an inferior overall survival." (PMID 33799782, 2021).
van Buchem’s disease (1 paper, 2021). "In van Buchem’s disease, there is a homozygous absence of ECR5 region, which has binding sites for the myocyte enhancer factor (Mef2c) transcription factor, suggesting that the binding of Mef2c to the ECR5 region of the SOST gene is important for SOST gene expression." (PMID 34830568, 2021).
tumor (65 papers, 2008 to 2025). "MEF2C is predominantly expressed in the tumor core of both LSCC and LUAD, underscoring its association with cancer cell proliferation and its potential regulatory interaction with STAT3." (PMID 41373817, 2025). "MEF2C that has been implicated as a pro-tumor repressor showed the highest binding potential by JASPAR76." (PMID 38802355, 2024). "MEF2C has previously been implicated in repressing pro-tumor macrophage function while promoting pro-inflammatory macrophage polarization." (PMID 38802355, 2024). "Nevertheless, in tumor-bearing mice, the preservation of SM mass induced by the inhibition of ActA is associated with the preservation of muscle MEF2C expression." (PMID 35406681, 2022). "MEF2C was traditionally considered a development-associated factor and can inhibit tumor growth in vitro and in vivo." (PMID 35910195, 2022). "We observed that cases with higher metastases number and greater tumor size presented the P3 phenotype, corresponding to nuclear translocation of MEF2C in all cells, indicating an association between MEF2C nuclear translocation and disease severity." (PMID 33673112, 2021). "MiR-223 remarkably prevented the differentiation of IMCs into MDSCs in the presence of tumor-associated factors by targeting myocyte enhancer factor 2C (MEF2C)." (PMID 33613512, 2020). "The association of C5aR1 and MEF2C expression with the expression of a number of other TFs suggests that they may also contribute to the regulation of pro-tumor macrophage function potentially through C5aR1." (PMID 38802355, 2024). "Interestingly, the presence of MEF2C nuclear staining in BC cells was associated with an increased number of metastases and larger tumor size, suggestive of a link between MEF2C’s translocation and disease severity." (PMID 37762600, 2023). "In addition, the preservation of SM mass, induced by inhibition of ActA, is associated with the preservation of muscle MEF2C expression in tumor-bearing mice." (PMID 35406681, 2022). "The enriched expression of STAT3, VCAM1, and MEF2C at the tumor core and invasive front underscores their role in shaping the tumor–stroma interface." (PMID 41373817, 2025). "In human cell line models of FN-RMS, NOTCH1 regulates expression of SNAI1, increasing the number of proliferative, tumor propagating cells by repressing expression of MEF2C." (PMID 39902277, 2024). "The genes Herc6, Kat7, Mef2c, Rbm15, and Shld3 were found to be upregulated in both the right and left tumors of the treated groups, suggesting a coordinated response in tumor inhibition." (PMID 39339213, 2024). "Emerging evidence implicates that MEF2C silencing repressed GPX4 protein expression in tumor cells under Erastin‐ or RSL3‐stimulated ferroptotic stress." (PMID 39350345, 2024). "Treatment of FN-RMS cell lines with trametinib, a MEK1/2 tyrosine kinase inhibitor, results in increased expression of differentiation TFs like MYOG and MEF2C, leading to terminal differentiation of tumor cells." (PMID 39902277, 2024). "MEF2C expression has been shown to increase during tumor progression and to increasingly translocate into the nucleus along brain metastatic growth in a mouse model." (PMID 37568789, 2023). "We therefore refer to the third tumor cluster as the “Mef2c-driven” group, which indeed had high Mef2c expression levels." (PMID 36950387, 2023). "MEF2C plays an important role in tumor pathogenesis and development, however, a limited number of studies have evaluated its functions in nervous system tumors." (PMID 34991657, 2022). "On the other hand, after being assembled into multi-protein complexes as transcription factors, MEF2C can be transformed into transcription activators or inhibitors under the control of tumor microenvironments to produce the opposite effects." (PMID 34991657, 2022). "Our analysis showed that MEF2C expression was upregulated in tumor tissues and was related to poor patient survival outcomes." (PMID 36059448, 2022).
tumor (continued). "Higher levels of miR-233 contained by EVs that are released by TAMs can be transported to the tumor cells of the breast, where they stimulate their invasiveness by the regulation of myocyte enhancer factor 2c (Mef2c)-β-catenin signaling cascade." (PMID 36430305, 2022). "In tumor-bearing mice, miR-223 reduces the accumulation of MDSCs and inhibits immature myeloid cells differentiation into MDSCs by targeting Myocyte enhancer factor 2C (MEF2C)." (PMID 35359390, 2022). "A study on brain metastases of breast cancer (BCBM) demonstrated that MEF2C, as a target gene of miR-802-5p and miR-194-5p, is increased in metastatic tumor cells." (PMID 34991657, 2022). "Specifically, MEF2C can control MyHC IIA expression, and cachexia decreases muscle MEF2C expression in C26 tumor-bearing mice." (PMID 34395422, 2021). "On the other hand, cytosolic MEF2C has been shown to inhibit tumor growth via Wnt/β-catenin (CTNNB1) signaling, which is involved in the regulation of cancer cell proliferation." (PMID 33673112, 2021). "As with the allograft data, these tumor studies indicated impaired Treg function in vivo after conditional Mef2c deletion." (PMID 34290714, 2021). "This indicates that MEF2C presents a dual role in tumor development depending on its cellular location and points to MEF2C as a new player in BCBM that deserves to be better unraveled, together with its partners VEGFR-2 and β-catenin." (PMID 33673112, 2021). "Analysis of MEF2C immunoreactivity showed a 24% increase in MEF2C expression/tumor area in metastasis throughout time, between 3 and 10 days (P < 0.01) and a 20% elevation between 7 and 10 days (P < 0.01)." (PMID 31930767, 2020). "This can indicate that MEF2C is involved in the crosstalk between astroglial cells and tumor cells during BCBM formation, to support tumor growth, which deserves further studies." (PMID 31930767, 2020). "Its upregulation was also observed in peritumoral astrocytes pointing to a role of MEF2C in the crosstalk between tumor cells and astrocytes." (PMID 31930767, 2020). "In reconstituted tumor models, miR-223 also suppressed accumulation of MDSCs, whereas its targeting molecule MEF2C increased in accumulated MDSCs accordingly." (PMID 27458169, 2016). "In xenograft tumors formed with SAHA-treated H460 H-INV cells, we detected increased density of staining for TGFBR2 and MEF2C in overall tumor cells." (PMID 27634890, 2016). "In conclusion, our results demonstrate that MEF2C restricts hESCs to the neuronal lineage and that this attribute can be used to generate neurons and avoid tumor formation when used for cell-based therapies." (PMID 21901155, 2011). "The positive correlation between SOX18 and MEF2C in LUAD, and the strong endothelial co-expression of SOX18 with VCAM1, suggests a coordinated transcriptional module possibly orchestrating endothelial activation in tumor-associated vasculature." (PMID 41373817, 2025). "In addition, among the enriched TFs in NN-HF, we further identified NFκB-P65, FOXA3, FOXD3, SIX1, CDX2, and MEF2C which have been found to impact tumor progression." (PMID 38720110, 2024). "MEF2C’s role in tumor development presents some duality accordingly with its subcellular location." (PMID 37762600, 2023). "We used a sphere formation assay to examine the effect of MEF2C on tumor cell stemness." (PMID 36059448, 2022). "According to these findings, we hypothesize that MEF2C may inhibit the cytotoxic T lymphocytes and activated DCs, thereby hindering the intratumoral anti-tumor immune response." (PMID 36059448, 2022). "Other miRNAs also presented the function of tumor-inhibiting, for instance, miR-233 remarkably slowed the progression of the tumor by repressing myeloid cell differentiation to MDSCs via targeting myocyte enhancer factor 2C (MEF2C)." (PMID 35634311, 2022).
tumor (continued). "We also verified that MEF2C affects the adhesion of tumor cells to the extracellular matrix by cell adhesion assays.The results showed that the adhesion of si-MEF2C cells to the extracellular matrix such as vitronectin and fibronectin was reduced compared with the control group." (PMID 36059448, 2022). "VEGF signaling is induced by nuclear MEF2C, increasing angiogenesis and tumor invasion." (PMID 33673112, 2021). "There are several evidences of MEF2C involvement in tumor progression." (PMID 33673112, 2021). "Here, we show that astrocytes start expressing MEF2C after tumor cell extravasation." (PMID 31930767, 2020). "In several mouse tumor models intravenous application of oligofectamine/miR-223 complexes inhibited tumor-conferred MDSC generation by targeting myocyte enhancer factor 2C (MEF2C) in bone marrow progenitor cells." (PMID 32917034, 2020). "The upregulated expression of the FLT3, MEF2C, NFKBIZ, and MDM2 genes in sarcoid AMs suggests the potential side effect of DEX and it may lead to increased risk of tumor cell proliferation." (PMID 32477331, 2020). "Moreover, MEF2C was increasingly expressed by tumor cells throughout time, which supports the involvement of this transcription factor in metastasis development." (PMID 31930767, 2020). "Importantly, MEF2C was recently identified as a candidate tumor suppressor gene in OS in a forward genetic screen." (PMID 27874835, 2016). "Lowest concentration values of MEF2C are present in almost all stages of tumor progression." (PMID 22952604, 2012). "We suggest on this basis that PRL-3 is a downstream component of the VEGF/MEF2C pathway in endothelial cells, and that it may play an important role in tumor angiogenesis." (PMID 22073279, 2011). "We suggest that PRL-3 functions downstream of the VEGF/MEF2C pathway in endothelial cells and may play an important role in tumor angiogenesis." (PMID 22073279, 2011). "Tumor 7107 also showed high Mef2c expression and has an insertion located 390 kb upstream of Mef2c." (PMID 19461887, 2009). "Therefore, MEF2C may act as a “double-edged sword” (either as a proto-oncogene or a tumor suppressor) in tumor pathogenesis." (PMID 34991657, 2022). "In this study, we aimed to establish whether MEF2C is expressed in human BCBM, and its association with relevant cancer-associated signaling pathways, such as VEGF and β-catenin, and whether its expression is tumor-specific." (PMID 33673112, 2021). "Indeed, several downstream targets of MEF2 involved in muscle structure and function were among the top FoxP1 target genes repressed in response to tumour burden, including Casq1, Casq2, Lmod3, Ky, and Mef2c —suggesting that FoxP1 up‐regulation disrupts MEF2 transcriptional activity." (PMID 33527776, 2021). "Furthermore, a nuclear translocation of MEF2C was observed in later stages of tumor progression." (PMID 31930767, 2020). "Spatial transcriptomics revealed SOX18 enrichment at tumor cores and invasive borders, co-localizing with MEF2C, VCAM1, and p-STAT3 in vascular and stromal niches, while SOX30 expression remained low across all tumor regions." (PMID 41373817, 2025). "In addition, the tumor-induced elevation of circulating ActA levels seems to be involved in the decrease in MEF2C muscle expression, since the inhibition of ActA activity allowed muscle mass and MEF2C expression to be preserved, supporting the relevance of our in vitro observations." (PMID 35406681, 2022). "miR-223 significantly inhibits the differentiation and accumulation of MDSCs as well as their suppressive function by targeting myocyte enhancer factor 2C (MEF2C) and inhibiting STAT3 signaling respectively in tumor-bearing mice." (PMID 36569895, 2022).